TXN (thioredoxin)
Diseases named in the same sentence as TXN in open-access papers (continued):
Sharing a sentence is not in itself a finding about the gene and the disease.
liver disease (3 papers, 2008 to 2023). "The level of thioredoxin tended to increase as liver disease progressed from Child-Pugh class A to C as well as tumor stage from I to IV." (PMID 25871387, 2015). "In addition, the level of thioredoxin tended to increase as liver disease progressed from Child-Pugh class A to C as well as tumor stage from I to IV." (PMID 25871387, 2015). "Thioredoxin is released from the cell in a redox-sensitive manner, and the serum thioredoxin level is considered to be an indicator of oxidative stress, especially in cases of liver diseases." (PMID 18983687, 2008).
mesothelioma (3 papers, 2013 to 2023). A usually malignant and aggressive neoplasm of the mesothelium which is often associated with exposure to asbestos. "The redox enzyme thioredoxin has been found to be upregulated in mesothelioma cell lines and biopsies, as detected by subtractive hybridisation, microarray and immunohistochemistry." (PMID 23991032, 2013). "Treatment with auranofin in mesothelioma cell lines resulted in an increased proportion of cells in the sub-G1 fraction which may indicate an apoptotic response to the thioredoxin inhibitor." (PMID 37298855, 2023). "Recently, thioredoxin concentrations in serum were shown to be predictive of mesothelioma." (PMID 23991032, 2013). "In the present study, thioredoxin in effusions were not predictive of mesothelioma, suggesting that the turnover of thioredoxin may differ between effusion fluids and serum." (PMID 23991032, 2013).
metabolic syndrome (3 papers, 2015 to 2025). A cluster of metabolic risk factors for CARDIOVASCULAR DISEASES and TYPE 2 DIABETES MELLITUS. "Moreover, we categorized metabolic syndrome-related characteristics in the study population by the TXN and COMT SNP genotype, but found that only age differentially-associated depending on the genotype of each SNP." (PMID 26329592, 2015).
myocardial ischemia (3 papers, 2016 to 2024). A disorder of cardiac function caused by insufficient blood flow to the muscle tissue of the heart. "Increased thioredoxin production occurs to lessen cellular injury caused by ROS in patients with myocardial ischemia." (PMID 35200704, 2022). "High levels of thioredoxin could indicate active myocardial ischemia activity." (PMID 35200704, 2022).
ovarian carcinoma (3 papers, 2014 to 2024). A malignant neoplasm originating from the surface ovarian epithelium. "In conclusion, the GnRH-R in ovarian cancer cells likely serves as a docking place for our GnRH-mitoxantrone conjugates, Con-3 and Con-7, which concentrates the mitoxantrone near the cell surface and exposes it to the extracellular thioredoxin system for release." (PMID 39274973, 2024).
psoriasis (3 papers, 2023 to 2025). An autoimmune condition characterized by red, well-delineated plaques with silvery scales that are usually on the extensor surfaces and scalp. "Oxidative stress related proteins such as Peroxiredoxin-5 (P30044) and thioredoxin (P10599) were more upregulated in psoriasis with CVD risk factors than in psoriasis without CVD risk factors in the current study." (PMID 36804462, 2023). "Moreover, TXNIP, also known as Vitamin-D upregulated protein-1 (VDUP-1), interacts with thioredoxin to regulate redox responses, and has been identified as a factor determining the pathogenesis of skin diseases (e.g., psoriasis) during keratinocyte differentiation." (PMID 41440888, 2025).
retinal degeneration (3 papers, 2022 to 2025). Degeneration of the retina. "Overexpression TXN downstream proteins, for example, MSRs or PRDXs, also exhibited the therapeutic potential to treat retinal degeneration." (PMID 36274523, 2022). "Sulforaphane, an isothiocyanate of plant origin, has shown its therapeutic properties in experimental models of retinal degeneration by activating NRF2, resulting in increased levels of TXN, TXNRD, and heme oxygenase-1 (HO-1)." (PMID 40867647, 2025). "Sulforaphane, a major isothiocyanate derived from cruciferous vegetables, has shown its therapeutic effect on retinal degeneration models via the activation of NRF2, resulting in the increased level of TXN, TXNRD, and heme oxygenase-1 (HO-1)." (PMID 36274523, 2022). "Also, increasing the expression of proteins downstream of the TXN pathway, such as MSR and PRDX, showed promising results as a therapeutic strategy for retinal degeneration." (PMID 40867647, 2025). "Furthermore, sulforaphane, an isothiocyanate from cruciferous vegetables, has demonstrated therapeutic effects in retinal degeneration models by activating NRF2, which upregulates antioxidant proteins like thioredoxin (TXN), thioredoxin reductase (TXNRD), and heme oxygenase-1 (HO-1)." (PMID 40002339, 2025).
vitiligo (3 papers, 2021 to 2025). Generalized well circumscribed patches of leukoderma that are generally distributed over symmetric body locations and is due to autoimmune destruction of melanocytes. "Regarding ECA25, six significant genomic regions were identified, although genes related to biological processes associated with vitiligo (TXN, LPAR1, SLC46A2, PRPF4, TRIM32, STOM, BRINP1, and DAB2IP) were only found in five of them." (PMID 39199954, 2024). "On the other hand, TXN was highly expressed in vitiligo skin samples and controlled the cellular redox environment." (PMID 34603063, 2021). "Further quantitative measurement of phosphorylated ASK2/total ASK2 levels is required for the involvement of the ASK2/TXN/TXNIP pathway in decreased KC GPNMB expression and vitiligo pathogenesis." (PMID 39947468, 2025). "These articulation proteins mainly included TXN (Thioredoxin), PBK, CDK1 (Cyclin-dependent kinase 1), which may be served as potential therapeutic targets for vitiligo." (PMID 34603063, 2021).
acute myeloid leukemia (2 papers, 2025). Acute myeloid leukemia (AML) is a group of neoplasms arising from precursor cells committed to the myeloid cell-line differentiation. "For example, the pathobiological and recurrence processes of acute myeloid leukemia-M5 (AML-M5) are significantly influenced by ROS-mediated interactions between thioredoxin (TRX) and c-Jun activation domain-binding protein-1 (JAB1)." (PMID 40563586, 2025). "Deregulation of WWP1 expression in acute myeloid leukemia (AML) blasts might accelerate TXNIP proteasomal degradation, thus increasing the ability of thioredoxin to buffer ROS, and ultimately favoring leukemic cell survival." (PMID 39364720, 2025).
acute promyelocytic leukemia (2 papers, 2022). An aggressive form of acute myeloid leukemia (AML), characterized by arrest of leukocyte differentiation at the promyelocyte stage, due to a specific chromosomal translocation t(15;17) in myeloid cells. "Arsenic trioxide (ATO), a thioredoxin inhibitor used against acute promyelocytic leukemia, potentiated MTX cytotoxicity in vitro in some of the ALL cell lines tested." (PMID 36531023, 2022).
cervical carcinoma (2 papers, 2015 to 2022). A carcinoma arising from either the exocervical squamous epithelium or the endocervical glandular epithelium. "Treatment with thioredoxin, a cellular protein oxidoreductase synthesized by TXN gene expression, in the human cervical carcinoma cell line HeLa inhibited intracellular NF-κB pathway activation." (PMID 35631174, 2022).
colitis (2 papers, 2014 to 2024). Inflammation of the colon. "Also, relief of IBD symptoms was observed along with increased expression of antioxidant enzymes such as SOD2 and TrxR-1, and decreased thioredoxin in L. fermentum Lf1-fed DSS colitis mice." (PMID 39849930, 2024). "The expression of “thioredoxin” was also found to be significantly (P < 0.000) downregulated in colitis-induced mice at the level of −4.292-fold with respect to noncolitis PBS control mice." (PMID 25061603, 2014).
diffuse large B-cell lymphoma (2 papers, 2016 to 2021). "TXN curtails p300-mediated FOXO1 acetylation and its nuclear translocation in response to oxidative stress, thus attenuates FOXO1 transcriptional activity toward genes involved in apoptosis and cell cycle inhibition in diffuse large B-cell lymphomas." (PMID 27835585, 2016).
endometriosis (2 papers, 2020 to 2021). The growth of functional endometrial tissue in anatomic sites outside the uterine body. "In order to further explore the role of the thioredoxin system and its impact on endometriosis, we chose to analyze SNP (rs1128446) of TXNRD1 gene, located on chromosome 12." (PMID 32679649, 2020). "It is probable to hypothesize endometriosis patients may also have overexpression of TXN genes, to allow for ectopic endometrial tissue to survive against oxidative stress." (PMID 32679649, 2020). "No significant risk of endometriosis by genetic variants was found in the TXN (rs4821494) in a codominant model." (PMID 32679649, 2020). "Extending previous research, we hypothesize that endometriosis patients may also have an overexpression of TXN genes, allowing ectopic endometrial tissue to proliferate." (PMID 32679649, 2020). "However, limited research is found between the TXN gene and endometriosis." (PMID 32679649, 2020). "Antioxidants such as vitamin C, vitamin E, thioredoxin, SOD, and glutathione have been found to be lower in follicular fluid from infertile patients with endometriosis than in women with non-endometriosis-related infertility." (PMID 34281188, 2021). "They then deduced the possibility of a mutual disproportion of TRX and TBP-2 in patients with endometriosis, leading to TBP-2 downregulation, which in turn negatively regulates TXN, decreasing its expression." (PMID 32679649, 2020).
epilepsy (2 papers, 2023 to 2026). A brain disorder characterized by episodes of abnormally increased neuronal discharge resulting in transient episodes of sensory or motor neurological dysfunction, or psychic dysfunction. "Thus, whether a thioredoxin-mimetic peptide can influence epileptogenesis, suppress chronic spontaneous seizures, or improve epilepsy-associated behavioral deficits remains unknown." (PMID 41544351, 2026). "In this context, thioredoxin-mimetic peptides represent a mechanistically distinct strategy centered on redox and inflammatory regulation; however, CB3 has not previously been evaluated in epilepsy." (PMID 41544351, 2026).
Glucose intolerance (2 papers, 2013 to 2023). Glucose intolerance (GI) can be defined as dysglycemia that comprises both prediabetes and diabetes. "For example, glucose intolerance was associated with the high levels of thioredoxin as a marker of oxidative stress, correlated to the presence of coronary artery disease (CAD)." (PMID 23691063, 2013).
gouty arthritis (2 papers, 2018 to 2022). "Recently, TXNIP, a known negative regulator of antioxidative protein thioredoxin, has emerged to be an attractive target in gouty arthritis, cervical inflammation, and CNS-related injury or diseases, implicating TXNIP as an important player in their pathogenesis." (PMID 29386025, 2018). "As a known negative modulator of antioxidant protein thioredoxin, TXNIP has emerged as a promising target in a number of diseases like gouty arthritis, cervical inflammation, and central nervous system-related injuries or diseases." (PMID 35845136, 2022).
hematoma (2 papers, 2021 to 2024). A hematoma is a collection of blood from a vascular structure into an extravascular space. "The other is associated with T cell subcluster 6, which is a hematoma cluster emerging during rebleeding, and is defined by T cell effector genes like CXCR4, TXN, and CSTB (effector module score 2)." (PMID 33749664, 2021).
Infertility (2 papers, 2021 to 2023). "Several studies have shown the importance of the thioredoxin/peroxiredoxin system in the testis, and higher infertility rates are observed in patients exhibiting a redox imbalance." (PMID 36918776, 2023).
insulinoma (2 papers, 2021 to 2023). "Small molecule thioredoxin mimetics to treat an insulinoma cell line, i.e., INS 832/13 cells, reduces cell death caused by the thioredoxin reductase inhibitor auranofin." (PMID 38001457, 2023). "Treatment of INS 832/13 cells, an insulinoma cell line, with small molecule thioredoxin mimetics attenuates cell death induced by treatment with the thioredoxin reductase inhibitor, auranofin." (PMID 34557160, 2021).
lung diseases (2 papers, 2023). "The elevation of thioredoxin is viewed as an adaptive response to lung inflammation associated with oxidative stress, and direct linkages between OS and the pathophysiology of many lung disorders have been demonstrated." (PMID 38001457, 2023).
metastatic cancers (2 papers, 2015 to 2025). A carcinoma which has spread from the original site of growth to another anatomic site. "In addition, increased expressions of TXN and TXNRD1 were correlated with clinical stage and distant metastasis in SACC patients, which supports previous report that TXN overexpression is an independent prognostic factor in metastatic cancers." (PMID 26325518, 2015).
non-small cell lung carcinoma (2 papers, 2013 to 2017). A group of at least three distinct histological types of lung cancer, including non-small cell squamous cell carcinoma, adenocarcinoma, and large cell carcinoma. "Previous studies had shown thioredoxin expression is associated with lymph node status and prognosis in early operable non-small cell lung cancer; however the prognostic significance of TrxR1 in NSCLC is still unclear." (PMID 29383158, 2017).
osteoporosis (2 papers, 2022 to 2023). A condition of reduced bone mass, with decreased cortical thickness and a decrease in the number and size of the trabeculae of cancellous bone (but normal chemical composition), resulting in increased fracture incidence. "Similarly, osteoporosis in ovariectomy animals caused a significant reduction in glutathione and thioredoxin levels." (PMID 36235920, 2022). "The analyzed polymorphisms belonging to a wide variety of genes, e.g., SOD, PON, GPx, GST, TXN, CAT, ALOX12, GSR, and NOS, focused on BMD variation, which is the current clinical gold standard for analyzing reductions in bone mass and diagnosing osteoporosis." (PMID 37107290, 2023).
pulmonary fibrosis (2 papers, 2010 to 2025). Chronic progressive interstitial lung disorder characterized by the replacement of the lung tissue by connective tissue, leading to progressive dyspnea, respiratory failure, or right heart failure. "The pulmonary fibrosis and inflammation induced by bleomycin were prevented in mice overexpressing thioredoxin." (PMID 20298567, 2010). "TXN/TXNRD1 inhibitors not only have anti-tumor activity, but also inhibit pulmonary fibrosis by inhibiting NF-κB/TGF-β1/Smads pathway." (PMID 39744566, 2025).
renal fibrosis (2 papers, 2017 to 2021). A final common manifestation of a wide variety of chronic kidney diseases characterized by glomerulosclerosis and tubulointerstitial fibrosis. "Sirtinol also blocked the inhibitory effect of losartan on the UUO-induced renal fibrosis, suggesting that the anti-fibrotic effect of losartan might be mediated at least in part through inhibition of ER stress via up-regulation of SIRT1, followed by induction of HO-1 and thioredoxin." (PMID 28146117, 2017).
schizophrenia (2 papers, 2015 to 2021). A major psychotic disorder characterized by abnormalities in the perception or expression of reality. "The same authors, in 2013, have confirmed that the plasma level of thioredoxin in patients with schizophrenia does not exceed reliably healthy controls and is associated with the level of cognitive abilities." (PMID 26029110, 2015). "For patients with schizophrenia, it is shown that in the first psychotic episode, plasma levels of α-tocopherol, ascorbic acid decrease, level of thioredoxin increases." (PMID 26029110, 2015). "Therefore, our finding of enriched actinobacterial taxa related to thioredoxin in FES could reflect the role of Actinobacteria taxa as redox sensors in response to host oxidative stress in schizophrenia." (PMID 34711862, 2021).
T-cell leukemia (2 papers, 2016 to 2023). A malignant disease of the T-lymphocytes in the bone marrow, thymus, and/or blood. "Although lacking an N-terminal signal sequence, the secreted human thioredoxin TXN1 was first identified as the adult T-cell leukemia-derived factor (ADF)." (PMID 37065139, 2023). "For example, TXNIP can serve as an inhibitor for the activity of thioredoxin, a mediator of glucose metabolism, a tumor suppressor in T-cell leukemia or other cancers or a critical regulator of the differentiation of natural killer cells." (PMID 27224916, 2016).
acute liver failure (1 paper, 2015). Rapid deterioration of liver function causing encephalopathy and coagulopathy. "Glutathione and thioredoxin are complementary antioxidants in the protection of mammalian tissues against oxidative–nitrosative stress (ONS), and ONS is a principal cause of symptoms of hepatic encephalopathy (HE) associated with acute liver failure (ALF)." (PMID 25161077, 2015).
AIDS (1 paper, 2013). A syndrome resulting from the acquired deficiency of cellular immunity caused by the human immunodeficiency virus (HIV). "Prior studies have shown that Se plays a crucial role in the regulation of glutathione (GSH) and thioredoxin (Trx) systems against oxidative stress and related diseases, such as AIDS progression through GPx and TrxRs." (PMID 23638060, 2013).
airway allergy (1 paper, 2024). "Further research on thioredoxin revealed the mechanism of the therapeutic effect of thioredoxin on airway allergy through the downregulation of interleukin-13 (IL-13) expression and eosinophil activity." (PMID 39403377, 2024).
Arthritis (1 paper, 2024). Inflammation of a joint. "In this study, we aimed to investigate the impact of EGFR overexpression on the response to the thioredoxin inhibitor and arthritis medication, auranofin and glutathione inhibitor L-buthionine-sulfoximine (L-BSO)." (PMID 39001381, 2024).
benign prostatic hyperplasia (1 paper, 2013). A non-cancerous nodular enlargement of the prostate gland. "The objective of this study was to determine whether or not the stromal biomarkers detected with a thioredoxin-targeted nanodevice could be used to distinguish the stroma associated with benign prostatic hyperplasia from that associated with PCA." (PMID 23762225, 2013).
carcinoma in situ (1 paper, 2020). "Thus, the high expression of TXN in the prostate of maternal LPD offspring could be related to the development of carcinoma in situ, as observed in older rats." (PMID 33049715, 2020).
cholestasis (1 paper, 2018). Impairment of the bile flow caused by obstruction within the liver, or outside the liver in the bile duct system. "We also show that constitutively expressed hBD-1 (and TXN) is induced by cholestasis in two different patient cohorts as well as BDL mice." (PMID 30100908, 2018). "Most interestingly, in the presence of cholestasis (in 17 of the 144 patient cohort, defined as serum bilirubin levels >1.2 mg/dl; mean 4.5 mg/dl) we found a significant induction of hBD-1 (about 2.5-fold) and TXN but not GRX." (PMID 30100908, 2018).
chondrosarcoma (1 paper, 2013). A malignant cartilaginous matrix-producing mesenchymal neoplasm arising from the bone and soft tissue. "The results showed that BDNF-induced migration and invasion ability, as well as MMP-1 up-regulation of chondrosarcoma cells, were greatly reduced by pretreatment with the ASK1 inhibitor thioredoxin." (PMID 23892595, 2013).
chronic granulomatous disease (1 paper, 2017). Chronic granulomatous disease (CGD) is a rare primary immunodeficiency, mainly affecting phagocytes, which is characterized by an increased susceptibility to severe and recurrent bacterial and fungal infections, along with the development of granulomas. "Relative basal expression of SOD2 and TXN in chronic granulomatous disease (CGD) monocytes compared to monocytes from healthy individuals." (PMID 29375548, 2017).